Y_RNA (Y RNA )
Gene: Miscellaneous RNA gene on chromosome 11 (43,331,261 to 43,331,356, forward strand). Ensembl gene ENSG00000252652.
Homologues: Orthologues: chimpanzee Y_RNA (100% identical), macaque Y_RNA (93% identical). Paralogues in human: RNY4 (83% identical), RNY4P6 (82% identical), RNY4P10 (81% identical), Y_RNA (81% identical), RNY4P14 (80% identical), RNY4P3 (80% identical), Y_RNA (80% identical), RNY4P25 (79% identical), RNY4P7 (79% identical), Y_RNA (79% identical), RNY4P13 (78% identical), RNY4P16 (78% identical), and 86 more.